RAB37 (RAB37, member RAS oncogene family)
Diseases named in the same sentence as RAB37 in open-access papers (continued):
Sharing a sentence is not in itself a finding about the gene and the disease.
lung carcinoma (continued). "To test whether PKCα phosphorylates Rab37 in lung cancer cell-based studies, we first detected the PKCα activity by measuring the phospho-substrates of PKCα in cells with overexpression of PKCα." (PMID 29312551, 2017). "We thus investigated whether Rab37 was phosphorylated in lung cancer cells by transfecting PC-14 cells with an empty vector (EV) or a plasmid carrying HA-tagged Rab37 wild-type (WT) insert." (PMID 29312551, 2017). "New diagnostic and therapeutic strategies based on detection of Rab37 phosphorylation and inhibitors against phosphorylated Rab37 could improve the survival in lung cancer patients." (PMID 29312551, 2017). "Based on our finding that overexpression of Rab37 mediated sustainable PD-1 PM presentation and T cell exhaustion, we thus proposed that the TIL populations of Rab37+/PD-1+/TIM3+/CD8+ T cells may be related to the adverse clinical responses in lung cancer patients." (PMID 38321486, 2024). "Importantly, multivariate Cox regression analysis revealed that lung cancer patients with high tumor-infiltrating Rab37+/PD-1+/TIM3+/CD8+ T cell profile (hazard ratio = 6.074, P = 0.001) still showed significantly high risk of death even after adjusting for other clinical parameters." (PMID 38321486, 2024). "Importantly, lung cancer patients with high infiltrating Rab37+/PD-1+/TIM3+ CD8+ T cells showed poor prognosis, suggesting that these tumor-infiltrating T cells are likely terminal exhaustion T cells with reduced proliferation and poor responses to immunotherapy." (PMID 38321486, 2024). "Notably, Rab37 expression level was increased in Jurkat T cells upon lung cancer CM treatment." (PMID 38321486, 2024). "Since Rab37 overexpression inhibited lung cancer stemness properties and was inversely correlated with expression of Oct4 stemness gene in vitro and in vivo, we further analyzed the clinical manifestations in patients with low Rab37, low SFRP1 and high Oct4 expression." (PMID 30158579, 2018). "These in vivo results indicated that Rab37 suppressed effector CD8 T cells, thereby promoting tumor growth in lung cancer." (PMID 38321486, 2024). "These database analyses and experimental results suggested that upregulation of Rab37 is involved in PD-1 expression and immune suppression in the TME of lung cancer." (PMID 38321486, 2024). "We reveal that activated Rab37 promotes the secretion of insulin in mouse β cells (Min‐6) and TIMP1 in human lung cancer cells (CL1‐5‐Q89L, harboring active Rab37), respectively." (PMID 38804615, 2024). "Herein, we demonstrated that the interaction between Rab37 and LC3 was increased in lung cancer cells under starvation conditions by immunoprecipitation analysis (lane 2), which leads to the promotion of TIMP1 exocytosis by the secretory autophagy." (PMID 36457117, 2022). "It has been reported that under serum-depleted conditions, Rab37-mediated exocytosis of TIMP1 suppresses MMP9, which leads to decreased metastases of lung cancer cells in vivo." (PMID 36457117, 2022). "We further validated the role of Rab37-autophagy-mediated TIMP1 secretion in tumorigenesis of lung cancer both in vitro and in vivo together with clinical lung cancer patient specimens." (PMID 36457117, 2022). "The lung-to-lung metastasis mouse model was prepared using lung cancer CL1-5 naïve, cells (Vector), and CL1-5-Q89L cells harboring active-form Rab37 transgene (Q89L)." (PMID 36457117, 2022). "The effects of Sec22b on Rab37 and autophagy-mediated TIMP1 secretion and tumorigenesis in lung cancer H460 cells." (PMID 36457117, 2022). "Our in vitro and in vivo data imply that secretory autophagy plays a promoting role in active-form Rab37-mediated TIMP1 secretion, which suppresses the motility of lung cancer cells." (PMID 36457117, 2022).
lung carcinoma (continued). "In contrast, we discovered that active-form Rab37 increased autophagic activity and TIMP1 secretion, which led to suppression of lung cancer cell metastasis from the right lung to the left lung, as well as a decrease in tumor nodules." (PMID 36457117, 2022). "In a suggested mechanism, Rab37 mediates exocytosis of secreted frizzled related protein 1 (SFRP1), an antagonist of the WNT pathway, to suppress WNT signaling in lung cancer cells in vitro." (PMID 36317486, 2022). "Our findings imply that autophagy together with Sec22b plays a pivotal role in Rab37-mediated TIMP1 secretion and tumorigenesis of lung cancer cells." (PMID 36457117, 2022). "Clinically, tumors with high stromal Rab37 and IL-6 expression coincide with tumor infiltrating M2-macrophages and PD1+CD8+ T cells that predicts poor prognosis in lung cancer patients." (PMID 34093869, 2021). "For example, Rab37 controls the exocytosis of TIMP1 to inhibit inactivated MMP9 and thereby suppresses lung cancer metastasis and controls the exocytosis of TIMP2 to inhibit inactivated MMP2 in nasopharyngeal carcinoma." (PMID 34141705, 2021). "In conclusion, this study demonstrated that Rab37 mediates SFRP1 secretion to inactive the Wnt signaling pathway, and thus results in suppressing lung cancer stemness properties." (PMID 30158579, 2018). "Clinical results confirm that concordantly low Rab37, low SFRP1, and high Oct4 stemness protein expression profile can be used as a biomarker to predict poor prognosis in lung cancer patients." (PMID 30158579, 2018). "We examined Rab37, TIMP1 and PKCα expression patterns in tumor specimens from 158 lung cancer patients and assigned protein expression levels into preserved, overexpressed and low expression by immunohistochemical analysis." (PMID 29312551, 2017). "Similar results of inhibitory effects of PKCα-mediated T172 phosphorylation of Rab37 on cellular distribution, Rab37-mediated TIMP1 and TSP1 secretion and motility suppression were observed in another lung cancer cell line A549." (PMID 29312551, 2017). "We previously identified a novel Rab small GTPase protein, Rab37, which plays a critical role in regulating exocytosis of secreted glycoproteins, tissue inhibitor of metalloproteinases 1 (TIMP1) to suppress lung cancer metastasis." (PMID 29312551, 2017). "Therefore, we hypothesize that Rab37 acts as a tumor suppressor in lung cancer." (PMID 29312551, 2017). "We already confirmed that either high glucose or serum starvation could activate Rab37 and induce secretory autophagy to promote exocytosis of insulin from β‐cell and TIMP1 from lung cancer cells." (PMID 38804615, 2024). "To verify whether Rab37+ST2L+CD206+ tumors elicited an immunosuppressive TME, we performed multi-color IF-IHC to detect Rab37, ST2L, and CD206 in surgical tumor specimens of 48 lung cancer patients." (PMID 38778059, 2024). "Our results provide the first evidence that Rab37 small GTPase mediates trafficking and membrane presentation of PD-1 to sustain T cell exhaustion, and the tumor promoting function of Rab37/PD-1 axis in T cells of TME in lung cancer." (PMID 38321486, 2024). "Moreover, phosphorylation on threonine 172 (T172) negatively regulates Rab37 activity, and impairs the Rab37-induced exocytosis of TIMP1, resulting in the suppression activity of Rab37 on lung cancer cell motility." (PMID 38695990, 2024). "Thus far, our results indicated that IL-33 promotes M2 macrophage polarization and an immunosuppressive TME, reducing cisplatin efficacy in lung cancer via IL-33/ST2L/NF-κB signaling and Rab37/ST2L trafficking." (PMID 38778059, 2024). "Rab37-mediated exocytosis of tissue inhibitor of metalloproteinase 1 (TIMP1), an inflammatory cytokine, under serum-depleted conditions which leads to suppression of lung cancer cell metastasis has been reported." (PMID 36457117, 2022).
lung carcinoma (continued). "Rab37 mediates the secretion of tissue inhibitor of metalloproteinase 1 (TIMP1), which inhibits the activity of MMP9, to suppress migration, invasion and metastasis in lung cancer." (PMID 35927755, 2022). "RAB37 plays a positive role in adipogenic differentiation of hADSCs, but a negative role in lung cancer cell migration." (PMID 34858503, 2021). "In addition, quantitative analyses showed a positive correlation between Rab37 and SFRP1 in 68.8% of 109 lung cancer patients (P < 0.001)." (PMID 30158579, 2018). "Moreover, high expression of stem cell marker Oct4 coincided with low expression of Rab37 and SFRP1 in lung cancer patients with poor clinical outcomes." (PMID 30158579, 2018). "Lung cancer patients with preserved Rab37, low TIMP1, and high PKCα expression profile correlate with worse progression-free survival examined by Kaplan-Meier survival, suggesting that PKCα overexpression leads to dysfunction of Rab37." (PMID 29312551, 2017). "We also show that Rab37 is phosphorylated by protein kinase Cα (PKCα) at threonine 172 (T172), leading to attenuation of its GTP-bound state, and impairment of the Rab37-mediated exocytosis of TIMP1, and thus reduces its suppression activity on lung cancer cell motility." (PMID 29312551, 2017). "To clarify whether Rab37 was involved in the endo-lysosomal trafficking pathway in our study, we analyzed the endosomal marker (EEA1) in purified autophagosomes under starvation conditions in lung cancer cells." (PMID 36457117, 2022). "Notably, Rab37 regulates the exocytosis of soluble ST2 (sST2) to extracellular compartment to act as a decoy receptor to interrupt IL-33/ST2L signaling in macrophages and mediates macrophage polarization to the M1-like phenotype in TME of lung cancer." (PMID 35927755, 2022). "The Rab37/IL-6/STAT3/PD-1 axis in immune cell models prompted us to determine whether concurrent blockade of IL-6 and CTLA-4 in vivo would provide a rational treatment to circumvent current PD-1-targeted immune-modulatory therapy for lung cancer." (PMID 34093869, 2021). "The relationship between Rab37 and SFRP1 expression has never been examined in human cancer patients; we therefore performed IHC on surgical tumor specimens from 109 lung cancer patients." (PMID 30158579, 2018).
non-small cell lung carcinoma (3 papers, 2016 to 2020). A group of at least three distinct histological types of lung cancer, including non-small cell squamous cell carcinoma, adenocarcinoma, and large cell carcinoma. "However, promoter hypermethylation of Rab37 gene leading to low expression of Rab37 mRNA and protein is associated with advanced metastasis in non-small cell lung cancer patients." (PMID 27716280, 2016). "We have previously cloned human Rab37 and found that Rab37 mRNA was down-regulated by promoter hypermethylation in non-small cell lung cancer patients." (PMID 29312551, 2017). "Similarly, Rab37 represents an anti-metastatic factor in non-small cell lung cancer (NSCLC) by inhibiting matrix metalloproteinase 9 (MMP9) activity both in vitro and in vivo." (PMID 31973201, 2020).
lung adenocarcinoma (2 papers, 2019 to 2024). A carcinoma that arises from the lung and is characterized by the presence of malignant glandular epithelial cells. "eIF3i, HSC71, MHC class I antigen, transketolase, citrate synthase, Rab-37, MLH1 and AGR2 might be putative biomarkers in HSP90 inhibition response in lung adenocarcinoma." (PMID 31370342, 2019).
renal cell carcinoma (2 papers, 2016 to 2020). "Upregulation of Rab37 and its interacting partner TMEM22 are found in renal cell carcinoma (RCC) and decrease in its level by siRNA reduces cancer cell growth, suggesting the oncogenic-like role of Rab37 in RCC." (PMID 27716280, 2016).
Alzheimer disease (1 paper, 2022). A progressive, neurodegenerative disease characterized by loss of function and death of nerve cells in several areas of the brain leading to loss of cognitive function such as memory and language. "Bioinformatics analysis has shown that RAB37 is differentially expressed in Alzheimer’s disease." (PMID 36187128, 2022).
autism (1 paper, 2024). Persistent deficits in social interaction and communication and interaction as well as a markedly restricted repertoire of activity and interest as well as repetitive patterns of behavior. "Dipk2b has been reported to alter neuronal cellular secretory pathways that are involved in autism while RAB37 is known to participate in membrane trafficking and in the regulation of TIMP1 exocytosis." (PMID 38351172, 2024).
cervical squamous cell carcinoma (1 paper, 2018). A squamous cell carcinoma arising from the cervical epithelium. "In addition, RAB37 protein was detected in abnormal nuclei in some cervical squamous cell carcinomas." (PMID 29229996, 2018). "Furthermore, immunofluorescence analysis of clinical tumours samples in humans showed markedly decreased RAB37 expression in prostate adenocarcinomas, prostate transitional cell carcinomas, stomach adenocarcinoma and cervical squamous cell carcinomas." (PMID 29229996, 2018).
diabetes (1 paper, 2013). "Exposure of insulin-secreting cells to proinflammatory cytokines, fatty acids or oxidized low-density lipoproteins, mimicking physiopathological conditions that favor the development of diabetes, resulted in a decrease in Rab37 expression." (PMID 23826383, 2013).
Hyperglycemia (1 paper, 2013). An increased concentration of glucose in the blood. "Our data indicate that the decrease in Rab37 expression is at least in part mediated by ICER, a transcriptional repressor that is believed to contribute to β-cell failure evoked by chronic hyperglycemia, hyperlipidemia and oxLDL." (PMID 23826383, 2013).
Lewis lung carcinoma (1 paper, 2022). "Therefore, we performed multiplex immunofluorescence immunohistochemistry (IF-IHC) on Lewis lung carcinoma (LLC) orthotopic allografts taken from Rab37 WT mice." (PMID 34987649, 2022).
lymph node metastasis (1 paper, 2021). "Of note, patients with high intratumoral CD45+Rab37+IL-6+ expression were significantly associated with advanced tumor stage (P < 0.001), lymph node metastasis (P = 0.025) and distal metastasis (P = 0.003)." (PMID 34093869, 2021).
muscular dystrophy (1 paper, 2024). Muscular dystrophy (MD) refers to a group of more than 30 genetic diseases characterized by progressive weakness and degeneration of the skeletal muscles that control movement. "Ggps1 is also involved in muscular dystrophy and promotes rab37-mediated autophagy." (PMID 39156629, 2024).
Obesity (1 paper, 2018). Accumulation of substantial excess body fat. "Furthermore, PLAGL1 may be implicated in lipid metabolism and obesity through its effect on IDI1, PNPLA1, JAK3, and RAB37 expression." (PMID 30082726, 2018).
prostate tumors (1 paper, 2013). "We also queried specific ucRNAs and found, for example, that uc.454 + A, which was the most down-regulated ucRNA in prostate tumors, was predicted to directly interact with Ras signaling pathway-related transcripts, like RIN2 and RAB37." (PMID 23409773, 2013).
cancer (19 papers, 2014 to 2024). A tumor composed of atypical neoplastic, often pleomorphic cells that invade other tissues. "Particularly in cancer, an extensive analysis is conducted in understanding the association between Rab37 and exocytosis in regulating different cancer hallmarks." (PMID 34401050, 2021). "Recent study showed that Ras-related protein Rab-37-mediated TSP1 secretion in cancer cells is associated with the inhibition of the migration and angiogenesis of surrounding endothelial cells in vitro and in vivo." (PMID 31817450, 2019). "The results showed that patients with high tumor-infiltrating Rab37+/PD-1+/TIM3+/CD8+ T cell signals correlated with cancer recurrence." (PMID 38321486, 2024). "The IF-IHC results in mouse allograft tumors prompted us to verify if tumors from cancer patients with high expression of both Rab37 and CHI3L1 (Rab37+CHI3L1+) also foster an immunosuppressive TME." (PMID 34987649, 2022). "Secreted TSP1 from cancer cells with Rab37 exocytic function inhibits the p-focal adhesion kinase (p-FAK)/p-paxillin/p-ERK migration signaling in both cancer epithelial cells and their surrounding endothelial cells." (PMID 35927755, 2022). "We have previously reported that Rab37 small GTPase mediates secretion of IL-6 in macrophages to promote cancer progression, whereas the roles of Rab37 in the intracellular trafficking and exocytosis of CHI3L1 are unclear." (PMID 34987649, 2022). "The size and number of metastatic cancer nodules in lungs were lower in Rab37 KO mice than in WT mice." (PMID 34093869, 2021). "Of these overlapping genes, several have been implicated in cancer migration/invasion or metastasis, including EPHB6, AGR2, RAB37, CST1, and B4GALNT3." (PMID 34270616, 2021). "Strikingly, IL-6 was localized in Rab37-associated vesicles in THP-1 cells, which was further enhanced by cancer-CM." (PMID 34093869, 2021). "Together, these results revealed that splenic T cells of Rab37 KO mice had enhanced proliferation, cytokine production and cytotoxicity against cancer cells." (PMID 34093869, 2021). "To further confirm the ultrastructure of Rab37-mediated vesicle recruitment of IL-6, we performed immuno-transmission electron microscopy on cancer CM treated THP-1 human monocyte cells." (PMID 34093869, 2021). "Reconstitution experiments indicate that SFRP1 secretion is crucial for Rab37-mediated cancer stemness suppression and treatment with SRPP1 recombinant protein reduces xenograft tumor initiation ability." (PMID 30158579, 2018). "Our findings reveal that Rab37-mediated SFRP1 secretion suppresses cancer stemness, and dysregulated Rab37-SFRP1 pathway confers cancer stemness via the activation of Wnt signaling." (PMID 30158579, 2018). "The molecular mechanism has broad physiological and pathological implications for understanding the role of RAB37 in autophagy promotion, and in particular, cancer prevention and early detection." (PMID 29229996, 2018). "A recent study indicated that RAB37 can suppress metastasis through the TIMP1-MMP9 pathway, highlighting an importance of RAB37 protein in cancer." (PMID 29229996, 2018). "Our study reveals the involvement of a novel component of the vesicular exocytic machinery mediated by Rab37 small GTPase in anti-cancer stemness." (PMID 30158579, 2018). "Together, these data indicated that SFRP1 secretion is crucial for Rab37-mediated cancer stemness suppression and treatment with rSRPP1 protein reduces tumor initiation ability." (PMID 30158579, 2018). "Therapeutic strategies such as alterations in DNA demethylation status of Rab37 gene and elevated stability of RAB37 protein may contribute to the development of cancer therapy." (PMID 38695990, 2024). "In addition, secreted frizzled-related protein-1 (SFRP1), an extracellular antagonist of Wnt, is a cargo protein of Rab37 in cancer cells." (PMID 35927755, 2022).